YAP1 (Yes1 associated transcriptional regulator)
Diseases named in the same sentence as YAP1 in open-access papers (continued):
Sharing a sentence is not in itself a finding about the gene and the disease.
sarcoma (continued). "Similarly, fusions involving driver genes largely or exclusively restricted to sarcoma (e.g. KMT2A::YAP1 in case 9) are readily detectable, as are the more sarcoma-specific copy number targets (e.g. COPS3 in case 17 and MYOCD in case 13)." (PMID 38997407, 2024). "YAP1 is overexpressed in a series of sarcomas, including chondrosarcoma." (PMID 33495462, 2021). "Similarly, sarcomas expressing high levels of YAP1 had a median survival of 3.4 years, whereas those with low levels of YAP1 had a median survival of 7.1 years." (PMID 27129148, 2016). "Indeed, RNAseq signature could help, in this context, to better classify the tumor as a YAP1::KMT2A sarcoma instead of a vascular tumor." (PMID 40879254, 2025). "Using a pooled genetic screen based on The Cancer Genome Atlas (TCGA), the researchers identified key genes, in particular YAP1 and wild-type KRAS, as critical drivers of sarcoma development." (PMID 41123840, 2025). "In sarcoma, PDLIM1 regulates the Hippo pathway by inhibiting E3 ligase AIP-4, which mediates YAP1 degradation." (PMID 39548074, 2024). "YAP1 is a commonly recurrent partner to KMT2A, and YAP1–KMT2A fusion-positive sarcomas exhibit sclerosing epithelioid fibrosarcoma-like histomorphology." (PMID 32461620, 2020). "Collectively, we identified a cohort of 34 sarcomas with KMT2A fusions (0.2%), and YAP1 was the predominant partner (n = 16 [47%])." (PMID 32461620, 2020). "Fusions between YAP1 and KMT2A were detected by RNA-based assays in all 16 sarcomas, six of which were additionally confirmed by orthogonal DNA-based assays." (PMID 32461620, 2020). "Our findings identify nuclear YAP1 and TAZ positivity as a common feature in subsets of sarcomas of soft tissue and bone and provide evidence of YAP1/TAZ-TEAD signaling as a specific liability to be considered as a new target for therapeutic intervention." (PMID 31873172, 2019). "While YAP1 represents a new player in MLS pathogenesis, alterations of various Hippo signaling intermediates have recently been found in other sarcoma subtypes." (PMID 30898787, 2019). "YAP1 S127A and KRAS G12V-Cdkn2a null-driven ERMS repress the expression of mostly different gene sets in sarcomas compared to differentiated skeletal muscle, but again approximately 20% (100 genes) of the down regulated genes are identical." (PMID 30353028, 2018). "Results showed that the tumor was in close proximity to the SEF group, admixed together with the other YAP1::KMT2A MUC4 negative SEF sarcomas." (PMID 40879254, 2025). "Clin Cancer Res 30:4957–4973.This reference is of importance as it defined novel genetic drivers (YAP1, KRAS) and vulnerabilities in high-grade sarcoma models, linking specific oncogenic programmes to sarcoma subtypes and revealing oxidative phosphorylation as a potential therapeutic target." (PMID 41123840, 2025).
sarcoma (continued). "Furthermore, FOXM1 was shown to directly interact with the YAP1 transcriptional complex via TEAD1, resulting in the co-regulation of numerous critical proliferation targets that enhance sarcoma progression." (PMID 34831091, 2021). "In each of the 15 sarcomas in which both the 5′ and 3′ breakpoints of KMT2A could be evaluated, two sets of breakpoints involving KMT2A and YAP1 were identified." (PMID 32461620, 2020). "Alterations in various effectors of the Hippo signaling cascade such as YAP1, LATS2 or SAV1 copy number variations have recently been described in a variety of sarcoma subtypes and point to a major role of aberrant Hippo signals in different soft tissue malignancies." (PMID 31873172, 2019). "Though well-studied in epithelial tumors, the specific downstream effectors of YAP1 in sarcomas are not well characterized." (PMID 30382078, 2018). "Thus, although some sarcomas are considered immunologically “cold,” our data suggest that cytotoxic T cell activation is a critical factor in UPS patient survival, and that modulating Yap1 and T cell activity may improve clinical outcomes." (PMID 38652549, 2024). "Grouping of all 264 sarcomas together including various histological types of sarcoma did not demonstrate a correlation between WWTR1 and YAP1 expression and overall survival (data not shown)." (PMID 27129148, 2016).
cholangiocarcinoma (29 papers, 2013 to 2026). A carcinoma that arises from the intrahepatic biliary tree (intrahepatic cholangiocarcinoma) or from the junction, or adjacent to the junction, of the right and left hepatic ducts (hilar cholangiocarcinoma). "On the one hand, regorafenib suppressed EMT in cholangiocarcinoma (CCA) cells by inhibiting the activity of yes-associated protein 1 (YAP1) and regulating EMT-related genes, including E-cadherin and SNAIL." (PMID 41154409, 2025). "Considering that Silmitasertib was well tolerated and has been approved by FDA for the treatment of cholangiocarcinoma, more preclinical and clinical studies are further needed in these lethal cancers with aberrant upregulation of CK2α and YAP1." (PMID 39827153, 2025). "In cholangiocarcinoma cells, YY1 upregulates lncRNA DLEU1, which competitively binds to miR-149-5p, elevating Yes-associated protein 1 (YAP1) expression." (PMID 38331879, 2024). "Recent research has revealed that losartan, another ARB, attenuates cholangiocarcinoma cell growth by inhibiting the oncogenic activity of YAP1, which also supports our findings." (PMID 37143164, 2023). "m5C and m6A modifications of LncRNA NKILA have been found to facilitate cholangiocarcinoma growth and metastasis through the miR-582-3p-YAP1 axis." (PMID 37308824, 2023). "In contrast, NKILA interacts with mir-582-3p regulated by m6A methyltransferase METTL3 and inhibits its expression, thereby accelerating cholangiocarcinoma progression through YAP1." (PMID 36333719, 2022). "We further determined the correlation between YAP1 and various downstream factors in cholangiocarcinoma patients." (PMID 35449153, 2022). "Clinicopathological features and YAP1 expression in HCCs and combined hepatocellular-cholangiocarcinomas (cHC-CCs)." (PMID 24086533, 2013). "YAP1 expression in each histologic component of combined hepatocellular-cholangiocarcinomas (classic type)." (PMID 24086533, 2013). "Clinicopathological characteristics of HCCs and combined hepatocellular-cholangiocarcinomas according to YAP1 expression." (PMID 24086533, 2013). "Therefore, we confirm that PIEZO1 promotes GC progression primarily through the activation of the YAP1 signature, which is consistent with studies on cholangiocarcinoma." (PMID 37983931, 2023). "YAP1 has been claimed to play a dominant role in the tumorigenesis of cholangiocarcinoma, but the related molecular mechanism or clinical strategy remains unclear." (PMID 35449153, 2022). "YAP1, a regulator of cell fate, is upregulated in multiple cancers and is significantly associated with histological differentiation, TNM stage, and poor prognosis in cholangiocarcinoma (CCA) and colorectal cancer." (PMID 29700328, 2018). "Furthermore, an increase in YAP1 activity has been observed in cholangiocarcinoma." (PMID 41513610, 2026). "YAP1 upregulates SOX2 via binding to TEAD on the promoter region of SOX2, ultimately promoting the proliferation of cholangiocarcinoma cells." (PMID 38331879, 2024). "On the other hand, it has been shown that YAP1 nuclear retention is stimulated through YAP1 phosphorylation in the tyrosine 357 (Y357) residue by SFK in human and mouse cholangiocarcinoma cells." (PMID 34693980, 2021). "Both YAP1 and TEAD were found to bind to NUAK2 super-enhancer regions in cholangiocarcinoma and mesothelioma cell lines, and acute overexpression of YAP1 upregulated NUAK2 mRNA and protein, while depletion of YAP1 or both YAP1 & TAZ each reduced NUAK2 expression." (PMID 38939918, 2024). "To compare the expression levels of YAP1 signaling pathway genes between tumor and normal tissue samples, we used the TIMER2.0 platform to evaluate the expression profiles based on the cholangiocarcinoma cohort (CHOL) obtained from TCGA (The Cancer Genome Atlas) database." (PMID 37173920, 2023).
esophageal squamous cell carcinoma (29 papers, 2007 to 2025). Esophageal squamous cell carcinoma (ESCC) is a type of esophageal carcinoma (EC) that can affect any part of the esophagus, but is usually located in the upper or middle third. "In addition, NEK2 stabilizes Yes1 associated transcriptional regulator (YAP1) via phosphorylation at Thr-143, promoting Esophageal Squamous Cell Carcinoma (ESCC) migration and proliferation." (PMID 38795132, 2024). "However, in human esophageal squamous cell carcinoma cells miR-141 appears to induce cisplatin resistance through the Yes-Associated Protein 1 (YAP1)." (PMID 24865582, 2014). "In esophageal squamous cell carcinoma, ectopic expression of miR-141 directly inhibits the YAP1-mediate cisplatin-sensitive pattern of cancer cells." (PMID 36624516, 2023). "The 18 studies included 2 studies detecting YAP1 expression in esophageal squamous cell carcinoma (ESCC), 9 in GC, and 7 in CRC." (PMID 30539010, 2018). "One previous report has demonstrated the ability of nicotine to induce Yap1 in esophageal squamous cell carcinoma (ESCC), and this occurred through nAChRs." (PMID 30322398, 2018). "Targeting TEAD4/YAP1 complex or SGK1 could find application in the treatment of esophageal squamous cell carcinoma." (PMID 33517828, 2021). "We found that in patients with nonsurgical esophageal squamous cell carcinoma, YAP1 amplification is an adverse prognostic factor associated with significantly shorter local recurrent‐free survival (LRFS) after definitive chemoradiotherapy." (PMID 31851786, 2020). "OTUB1 and OTUB2 potentiated esophageal squamous cell carcinoma (ESCC) proliferation and metastasis by regulating the stability of Snail and YAP1/TAZ proteins, respectively." (PMID 40469292, 2025). "MiR-34a-5p played an anti-esophageal squamous cell carcinoma (ESCC) role by targeting the Hippo-YAP1/TAZ signaling pathway while the expression of LEF1 was high in ESCC tissue and cell lines." (PMID 34299149, 2021). "The overexpression of miR-141 can suppress the resistance of esophageal squamous cell carcinoma (ESCC) to cisplatin which is mediated by YAP1 gene." (PMID 25342041, 2014). "YAP1 is an important target gene for many malignant cancers, such as HCC, papillary thyroid cancer, GC, and esophageal squamous cell carcinoma (ESCC)." (PMID 40248198, 2025). "In esophageal squamous cell carcinoma, KIF4A inhibits YAP1 phosphorylation, leading to enhanced nuclear YAP1 protein level." (PMID 37039264, 2023). "Recent studies have demonstrated a link between Nic exposure and YAP1 activity in non-small cell lung cancer (NSCLC) and esophageal squamous cell cancer (ESCC)." (PMID 32894161, 2020). "Whether SOX2 and ACTL6A/TP63 interact with the Hippo‐YAP1 pathway in esophageal squamous cell carcinoma (ESCC) remains unclear." (PMID 31560173, 2019). "YAP1 induces KIF4A transcription by binding to the KIF4A promoter via TEA domain transcription factor 4 (TEAD4), contributing to the progression and poor prognosis of esophageal squamous cell carcinoma." (PMID 37039264, 2023).
mesothelioma (27 papers, 2017 to 2025). A usually malignant and aggressive neoplasm of the mesothelium which is often associated with exposure to asbestos. "Together, NF2 loss, YAP1 amplification, and LATS1/2 inactivation highlight the central role of this pathway in mesothelioma." (PMID 40362535, 2025). "It has been demonstrated that CTGF expression was regulated by TGF-β signaling, upstream of YAP1 in mesothelioma." (PMID 37686215, 2023). "Mesothelin (MSLN), Wilm’s tumor protein WT1 and YAP1, which are well-known tumor markers in mesothelioma cells, have been applied as therapeutic targets and prognostic indicators." (PMID 34768716, 2021). "We are interested in the role of ACTL6A in mesothelioma, as YAP1/TAZ function is required for optimal mesothelioma cancer cell survival." (PMID 34689163, 2021). "The purpose of that study is to characterize the safety and tolerability of IAG933 in patients with mesothelioma, NF2/LATS1/LATS2-mutated tumors and tumors with functional YAP1/TAZ fusions, as well as to identify the maximum tolerated dose." (PMID 34685695, 2021). "VP and CA3 weakened spheroid formation, matrix invasion, and tumor formation of the mesothelioma stem cells by inhibiting YAP1/TEAD." (PMID 33178014, 2020). "Treatment of the cells with exogenously transduced wild-type YAP1, and even more so, with an activated mutant YAP1 S127A, stimulated the mesothelial cells to form mesothelioma-like tumors." (PMID 29565815, 2018). "In addition, YAP1 amplification is commonly observed in primary mesothelioma tumors, further supporting the role of Hippo signaling pathway disruption in mesothelioma development." (PMID 40362535, 2025). "Notably, inactivation of Hippo pathway components NF2 and LATS1/2 are common in mesothelioma and result in constitutive activation of the YAP1/TAZ transcriptional coactivators, thereby conferring malignant phenotypes to mesothelial cells." (PMID 38784478, 2024). "The involvement of Hippo pathways in our results supports previous suggestions that YAP1 axis inhibition may be used in mesothelioma therapy." (PMID 34580349, 2021). "Moreover, YAP1—a downstream effector of the Hippo signaling pathway—is also activated in mesothelioma as a result of DNA amplifications and has been proposed as one of the few clinically actionable options in mesothelioma." (PMID 30060501, 2018). "Collectively, these data suggest that HA is an “unfavorable” factor because it promotes malignancy in mesothelioma and that the YAP1/TAZ-RHAMM axis may have potential value as a therapeutic target for inhibition of disease progression in MPM." (PMID 29212185, 2017). "Several pharmacological inhibitors of YAP signaling are currently being developed, most of them inhibiting the interaction of YAP1 with TEAD transcription factors, and their efficacy is being evaluated for other cancers, such as NF2 mutant mesothelioma." (PMID 38571886, 2024). "Previous studies have shown that CA3, a novel YAP1/TEAD4 transcriptional activity inhibitor, targets cancer stem cells in esophageal adenocarcinoma and mesothelioma." (PMID 36180487, 2022). "A number of selective inhibitors of the TEAD family members are in development and have been shown to disrupt YAP1/WWTR1/TEAD-dependent transcription, affect the viability of NF2 mutant mesothelioma models, and to enhance the efficacy of EGFR inhibitors in EGFR mutant lung cancer." (PMID 38658677, 2024). "Additionally, compound selectivity was further demonstrated by correlating RNA-sequencing (RNA-seq) gene expression changes from shRNA-mediated YAP1 knockdown and YTP-75 treatment in the NCI-H2052 mesothelioma cell line." (PMID 38565920, 2024). "Of note, YAP1/TAZ activation has been previously shown to confer malignant phenotypes to mesothelial cells and conditional (mesothelium-specific) NF2 knockout mouse models exhibited an increased incidence of mesothelioma development." (PMID 31959902, 2020).
mesothelioma (continued). "In addition, YAP1 is negatively regulated by large tumor suppressor kinases (LATS1 and LATS2), which are commonly deleted in mesothelioma; in contrast, forced expression of LATS2 inactivates YAP1 and causes a reduction in cell growth." (PMID 29342862, 2018). "It is known that the persistently active YAP1 expression abolishes the action of the inhibitors, which leads to the hypothesis that impairment of the YAP1/TAZ/TEAD signaling is a prerequisite for the effectiveness of Verteporfin and CA3 in mesothelioma cells." (PMID 33043017, 2020). "In the present study, we found that the YAP1/TAZ-RHAMM axis is involved in the regulation of migration and invasion in MPM cell lines, and that HA, which is massively present in pleural effusion in MPM patients, may contribute to the progression of mesothelioma." (PMID 29212185, 2017). "Additionally, the signal of H3K27ac, YAP1, JUN and FOSL1 was enriched in YREs specifically scoring in mesothelioma cells and not in common- or UM-specific hits." (PMID 37400441, 2023).